IL6 (interleukin 6)
Diseases named in the same sentence as IL6 in open-access papers (continued):
Sharing a sentence is not in itself a finding about the gene and the disease.
Hepatitis (220 papers, 2008 to 2026). Inflammation of the liver. "TNF-α causes damage to hepatocytes and induces the production of IL-1β and IL-6, thereby causing hepatocyte apoptosis and liver inflammation." (PMID 38999886, 2024). "These inflammatory cytokines, such as TNF-α, IL-6, and C-reactive protein, can induce liver inflammation and fibrosis, causing liver cell damage and interfering with liver function." (PMID 38076231, 2023). "Liver immune cells and the proinflammatory cytokines they produce, including Interleukin 6 (IL-6), Tumor Necrosis Factor Alpha (TNFα) and Interleukin 1 beta (IL-1β), have all been implicated in driving behavioral changes in the setting of liver inflammation." (PMID 37521690, 2023). "According to our findings, a low-vitamin B12 diet raises proinflammatory cytokines similar to TNF-a and IL-6, activating Kupffer cells (liver macrophages) and causing liver inflammation, whereas rosella extract treatment lowers proinflammatory cytokines." (PMID 37374248, 2023). "Next, we tested the levels of IL-6 in the serum which has been shown to cause damage to the liver cells during ConA-induced hepatitis." (PMID 35720411, 2022). "IL-8 is a pro-inflammatory mediator that induces chemotaxis of neutrophils and is associated with hepatitis caused by leptospirosis, whereas IL-6 disrupts the endothelial barrier and is associated with pulmonary hemorrhage syndrome." (PMID 35919644, 2022). "Il-1 β is associated with the formation of liver fat and liver degeneration, and IL-6 is associated with liver inflammation and fibrosis." (PMID 35584453, 2022). "The pathogenic roles of IL-1α, TNF-α, IFN-γ, and IL-6 in Con A-induced hepatitis have been extensively established in previous studies 39-42." (PMID 32641985, 2020). "The SNPs of the IL-6 gene have been reported to influence the histologic progression and clinical outcomes of HCV patients but there is a great disparity in the correlation between IL-6 gene polymorphisms and hepatitis-related HCC according to the literature." (PMID 32266003, 2020). "The initial analysis on the detection of inflammatory factors in the liver such as TNF-ɑ, IL-1β, IL-6, and iNOS revealed the association between hepatitis and monocyte-macrophage cells." (PMID 29599918, 2018). "It is a common perspective that the progress of hepatitis is associated with a series of proinflammatory cytokines such as IL-2, IL-6, IL-1β and TNF-α." (PMID 24498418, 2014). "TNF-α, IL1β and IL-6 are the cytokines most commonly associated with liver inflammation, while CD64 and CD68 are markers of Kupffer cell activation." (PMID 23755290, 2013). "Since cytokines in the serum had been reported to be associated with liver inflammation and dysfunction, patients with liver dysfunction had significantly higher level of IL-2R, IL-6, IL-10, and TNF-α in the serum, when compared with those without liver dysfunction (p < 0.001)." (PMID 29109622, 2017). "Thus, treatment with NAC attenuated the release of ConA-induced hepatitis-associated cytokines, such as IL-2, IL-6, IFN-γ, and TNF-α." (PMID 25821351, 2015). "The underlying mechanism of liver inflammation could present a common cytokine profile with skin lesions in SS (for instance, IL-1, IL-6, G-CSF) or a distinct one (IL-8, GM-CSF, and IFN-γ) in liver involvement, both leading to neutrophil activation and infiltration." (PMID 41156056, 2025). "Such chronic condition was further supported by a significant decrease in circulating levels of IL-6, a cytokine known to exert anti-inflammatory activities by controlling the level of pro-inflammatory cytokines, and the deficiency of which has been correlated with signs of liver inflammation." (PMID 36232456, 2022). "Moreover, IL-6−/− mice have hematopoietic deficiencies that may include other cell lines such as B cells that may also be critical to developing hepatitis following TFA-S100 immunizations." (PMID 23577207, 2013).
Hepatitis (continued). "Laboratory tests revealed thrombocytopenia (51 × 109/L), microangiopathic hemolysis with schistocytes, hepatitis (aspartate aminotransferase 995 U/L), and hyperinflammation (interleukin-6 >500 pg/mL, procalcitonin 35.3 ng/mL)." (PMID 41909338, 2026). "Excessive dietary Ile promoted liver inflammation and interleukin-6 release (P < 0.05), which acted on the pancreas to enhance insulin secretion." (PMID 41668211, 2026). "Studies on oleanolic acid (a key constituent of akebia) have demonstrated its capacity to suppress the production of pro-inflammatory cytokines, including IL-6 and IL-1β, by inhibiting the NF-κB signaling pathway in murine models of liver inflammation." (PMID 41295685, 2025). "Both TNF-α and IL-6 are key pro-inflammatory cytokines, and their measurement confirms the presence of liver inflammation." (PMID 41155639, 2025). "Studies have shown that such diets elevate inflammatory markers like C-reactive protein (CRP) and interleukin-6 (IL-6), contributing to vascular damage, arterial stiffness, and worsening liver inflammation and fibrosis, thereby accelerating MASLD progression." (PMID 40242166, 2025). "On the contrary, other authors supported that chronic activation of IL-6 signaling in the liver promoted hepatic IR and that IL-6 deletion (il6−/−) or pharmacological inhibition of IL-6 in mice on MCD diet attenuated NASH." (PMID 40794228, 2025). "Despite their proinflammatory status, the liver MSC secreted cytokines, such as IL-6 and IL-8, also perform a regenerative function during acute and chronic liver inflammation." (PMID 39769138, 2024). "In HBV infection, on the one hand, IL-6 can eliminate the virus by stimulating an immune response via infected hepatocytes; on the other hand, it can induce the occurrence of hepatitis, LC and HCC." (PMID 38693593, 2024). "Clinical evidence from a meta-analysis of 18 studies involving patients with HCC and hepatitis revealed a progressive elevation in serum IL-6 levels with disease progression, from healthy individuals to hepatitis, cirrhosis, and ultimately HCC." (PMID 38304429, 2024). "Evermore, multivariate regression analysis of the current findings revealed that IL-6 and TLR2 genotypes (SNP; rs3804099) were independent risk factors for progression of liver disease from inactive carrier state to active hepatitis state." (PMID 35119591, 2023). "Meanwhile, viral load, IL-6 and TLR2 genotypes were independent risk factors for progression of liver disease from active hepatitis state to cirrhotic liver disease." (PMID 35119591, 2023). "The inflammatory cytokines IL-1β and IL-6 were evaluated for their anti-inflammatory effects on alcohol-induced liver inflammation." (PMID 36788475, 2023). "Increasing levels of LPS activate Toll-like receptor 4 signaling pathways, produce proinflammatory cytokines, such as IL-17, TNF-α, IL-6, and IL-1β, and promote liver inflammation." (PMID 38138294, 2023). "Our study showed significantly higher IL-6 concentrations in both EBV-infected children with hepatitis and those with hepatocyte and biliary pole damage." (PMID 37834802, 2023). "HDGF induces TNF-α/IL-1β/IL-6/COX-2 signaling in response to concanavalin A-induced hepatitis in vitro and in vivo." (PMID 37827291, 2023). "Clinically, a recent meta-analysis of 18 studies including approximately 1000 HCC and hepatitis patients showed stepwise elevation of serum IL-6 levels according to the disease stage from healthy to hepatitis and cirrhosis and to HCC." (PMID 35205631, 2022). "TNF-α, IL-1β, and IL-6 are crucial cytokines involved in the occurrence and development of liver inflammation." (PMID 36144271, 2022). "The results showed that IL-1β and IL-6 levels were increased in the APKO-DEN hepatitis mice compared with WT-DEN mice, but the IL-12p70 and TNFα levels did not change significantly." (PMID 33558702, 2022).
Hepatitis (continued). "In a previous study, adipose tissue-derived autologous MSCs-derived exosomes attenuated renal inflammation, decreased TNF-α, IL-6, and IL-1-β in the renal vein, and reduced the serum levels of TNF-α, IFN-γ, IL-6, IL-18, and IL-1β in a hepatitis model." (PMID 35279651, 2022). "Of particular interest is the fact that let-7a, a member of the let-7 family of miRNAs, was shown to decrease IL-6-dependent Th17 differentiation and production of Th17-specific cytokines in a murine model of Con A-induced hepatitis." (PMID 35058939, 2021). "Systemic inflammatory response, including TNF, IL-8, IL-6, and IL-2, contributes to the transition from stable chronic liver disease to HBV-ACLF, which is associated with morbidity and mortality of hepatitis." (PMID 33868273, 2021). "Selection of these biomarkers was made based on the literature data suggesting that TNF-α, IFN-γ, IL-6, and IL-10 are important mediators in the development of ConA-induced hepatitis, and activities of transaminases are reliable indicators of liver damage." (PMID 33919375, 2021). "The results of earlier studies suggest that the inflammatory mediators IFN-γ, TNF-α, and IL-6 play a critical role in ConA-induced hepatitis as well as in the development of AIH in humans." (PMID 33919375, 2021). "Activated macrophages produce pro-inflammatory factors, such as TNF-α, IL-6, and IL-1β, which induce liver inflammation and injury." (PMID 35069557, 2021). "This is in line with the previous findings indicating that IL-6 present at the early stage of ConA-induced hepatitis triggers hepatoprotective pathways." (PMID 33919375, 2021). "On the other hand, there are some studies showing that IL-6 is a potential inflammatory mediator in NAFLD development and that the hepatic expression of IL-6 positively correlates with the stage of liver inflammation." (PMID 32751983, 2020). "In our study, the elimination of KCs completely protects against Con A-induced hepatitis by decreasing serum inflammatory cytokines such as IL-1α, TNF-α, IFN-γ, MCP-1, IL-12, and IL-6, relevant to Con A-induced hepatitis 39-42." (PMID 32641985, 2020). "In the present study, we found that hVNS regulates hepatic expression of inflammatory cytokines TNF-α, IL-1β, and IL-6 in Con-A model of hepatitis and also increases the expression of ChAT gene in the DMV neurons." (PMID 33272194, 2020). "In the immune clearance period, TGF-β synergizes with IL-6 or IL-21 to promote the differentiation of Th17 cells and liver inflammation." (PMID 30949222, 2019). "The proinflammatory cytokine IL-6, considered an acute phase protein, is increased in conditions of liver damage and hepatitis." (PMID 31049358, 2019). "On the other hand, transactivation of the complexes IL-6/STAT3/lncTCF7 or IL-6/STAT3/Snail-Smad3/TGF-β1 promotes the invasion of HCCs developed in patients with hepatitis, especially the nonalcoholic type." (PMID 31781608, 2019). "Studies have associated the induction of hepatitis with innate immunity and acquired type 1 pro-inflammatory response including TNF-α, IL-1β, IL-6, and IL-12." (PMID 31611801, 2019). "It was concluded that ARC alleviated cell autophagy and apoptosis via the inhibition of IFN-γ/IL-6/Stat1 signaling in ConA-induced hepatitis." (PMID 30177931, 2018). "Although we found increased IFN-γ mRNA level in the intestine and elevated IL-6 and IFN-γ serum levels in hosts receiving IL-17C−/− graft, decreased IL-6 and IFN-γ productions were detected in hepatitis with IL-17C deficiency." (PMID 30534126, 2018). "For example, higher concentrations of interleukin-1, interleukin-6, and tumor necrosis factor-α were found with several liver diseases, such as cirrhosis, hepatitis, and alcoholic liver disease." (PMID 30083134, 2018). "It was reported that IL-6 produced by KCs played a significant role in the pathogenesis of ConA-induced hepatitis." (PMID 30177931, 2018).
Hepatitis (continued). "Blockade of IL-6 signaling aggravates liver injury and lethality in a D-galactosamine N (GalN)/LPS hepatitis model." (PMID 28714885, 2017). "For instance, mice with interleukin-6 or tumor necrosis factor α receptor defect are protected from steatosis and hepatitis induced by high fat diet." (PMID 28824700, 2017). "They further showed that phosphorylated Stat3 and IL-6 were reduced in ConA-induced hepatitis, whereas p21 and Smad2 increased." (PMID 28330461, 2017). "Adipokines, such as IL-6 and TNF-α, produced during chronic inflammation of hypertrophied white adipose tissue are thought to cause hepatocyte fat accumulation and liver inflammation." (PMID 29022011, 2017). "It is well known that the progression of hepatitis is closely associated with inflammatory factors including TNF-α, IFN-γ, IL-1β, IL-2, IL6 and iNOS." (PMID 27035150, 2016). "Infected mice developed typical signs of hepatitis within 24–72 h post infection and during this period, pro-inflammatory cytokines, including interleukin (IL)-1β, IL-6, and tumor necrosis factor (TNF) α were secreted at the active sites of infection." (PMID 26739172, 2016). "Our study showed that IL-6 is stimulatory as suggested by higher levels in hepatic tissue and upregulation of target genes in mice with amphotericin B and flucytosine-induced liver inflammation." (PMID 26949702, 2016). "He demonstrated normal levels of IL-6 and severely decreased during the first week and gradually increased IL-1 levels during the further course of hepatitis A." (PMID 27716426, 2016). "Together, these data demonstrated that the protective role of salidroside pretreatment in Con A-induced hepatitis is associated with reduction of TNF-α, IFN-γ, and IL-6." (PMID 24808635, 2014). "The important regulatory roles are played by adipokines including interleukin-1β, interleukin-6, tumor necrosis factor-α, monocyte chemotactic protein-1, and adiponectin, ultimately reducing hepatitis and decreasing serum alanine aminotransferase release." (PMID 24816278, 2014). "We have shown that ethyl pyruvate is able to prevent Con A-induced hepatitis by down-regulating the production of inflammatory cytokines such as IL-2, IL-6, IL-1β and TNF-α." (PMID 24498418, 2014). "Treg transfer from naïve female mice to those with DILI reduced hepatitis severity and hepatic IL-6." (PMID 23577207, 2013). "A recent study shows that, in ConA-mediated hepatitis, IL-6 can also inhibit the activity of NKT cells in a CD4+ T cell and STAT3-dependent manner." (PMID 21394214, 2011). "In this study, we investigated the role of IL-6 in CD8+ T cell-mediated hepatitis triggered by anti-CD137 mAb." (PMID 21394214, 2011). "Pharmacological inhibition of Stat3 activity within the liver blocked the ability of IL-6 to prevent liver inflammation and to normalize the T/HS-induced liver inflammation transcriptome." (PMID 21738667, 2011). "Simultaneously, stigmasterol can also inhibit the activation of the nuclear factor-κB (NF-κB) pathway, reduce the secretion of inflammatory factors such as tumor necrosis factor-α (TNF-α), interleukin-6 (IL-6), and interleukin-1β (IL-1β), and alleviate liver inflammation." (PMID 40363681, 2025). "Second, IL-6 activates neutrophils to produce reactive oxygen species, enhancing the adhesion of neutrophils to endothelium and promoting inflammatory reactions, eventually leading to hepatitis, fibrosis, and cirrhosis." (PMID 40333907, 2025). "In the liver, IL-6 levels gradually increase from a healthy state to hepatitis, cirrhosis and HCC." (PMID 38304429, 2024). "The current study revealed significant increased levels of both cytokines IL-6 and IL-10 among those who were good responders to the hepatitis B vaccine boosters, with a significant positive correlation between these cytokines (IL-6 and IL-10) and anti-HBsAb titre." (PMID 38827254, 2024).
Hepatitis (continued). "Moreover, activation of IL-6 effector signaling is positively correlated with age-related dysregulation of lipid metabolism, hepatitis, fibrosis, and xenobiotic detoxification." (PMID 38890694, 2024). "The results of the present study showed that the IL-6-JAK-STAT signaling pathway may mediate the protective effects of IPOC against the hepatic IR injury as demonstrated by histopathology, IL-6, AST, ALT, and apoptosis assays." (PMID 38585457, 2024). "It appears that an increase in IL-6, TNF-α, and s-ICAM-1 in the course of EBV infection may indicate the risk of hepatitis with concomitant biliary pole damage." (PMID 37834802, 2023). "TT genotype was significantly related to lower IL-6 levels in active hepatitis and cirrhotic groups (P = 0.005 and P = 0.001, respectively) showing that TLR mutations would be associated with milder hepatitis activity and lower possibility for disease progression." (PMID 35119591, 2023). "Increased concentrations of IL-6, TNF-α, and s-ICAM-1 may indicate the risk of hepatitis with concomitant biliary pole damage during EBV infection." (PMID 37834802, 2023). "Liver inflammation, on the other hand, was assessed through the levels of IL-6, TNFα, and IL-1β." (PMID 37296638, 2023). "IL-6 prevents liver inflammation via suppression of NK cells, since administration of IL-6 markedly attenuated the ability of NK cells to kill hepatocytes in vitro, which has been suggested to play an important role in the pathogenesis of hepatitis." (PMID 37593740, 2023). "The production of IL-6 and IL-6 induced liver inflammation in mice." (PMID 36833499, 2023). "Furthermore, we detected pro-inflammatory cytokines TNF, IL-1β, IL-12p70, IFN-γ, IL-6, IL-2, and IL-17A corresponding with ConA-induced hepatitis and found that pro-inflammatory factors all rise at 6 h after ConA injection." (PMID 36248904, 2022). "However, at the critical 3 dpi timepoint when most C57BL/6 mice succumbed to hepatitis, nearly all measured C57BL/6 analyte levels were highly elevated including IL-6 and HGF, two inflammatory markers associated with the liver." (PMID 35834486, 2022). "Moreover, IL-6 is associated with the protein level of PHB1 in hepatitis; however, the role of the PHB1/IL-6/STAT3 signalling pathway in the development of hepatitis is controversial." (PMID 35847581, 2022). "Moreover, the over-expression of inflammatory factors such as interleukin-1β (IL-1β), interleukin-6 (IL-6) and tumor necrosis factor-alpha (TNF-α) induced by FAdV-4 caused hepatitis and further necrosis." (PMID 35590365, 2022). "Therefore, the up-regulation of IL6 expression is, on the one hand, a response to LPS-induced liver inflammation, and on the other hand, its overexpression can further lead to liver injury." (PMID 36611736, 2022). "Similarly, in animal models, serum IL-6 levels were also found to increase in relation to the degree of liver inflammation and fibrosis, suggesting that the three IC extract doses have potential inhibitory effects on liver inflammatory factors." (PMID 35630624, 2022). "Furthermore, patients with CHB, cirrhosis, and chronic LF had significantly higher plasma IL-6 level, and more severe liver inflammation." (PMID 34805027, 2021). "The activation of the NF-κB signaling pathway leads to the phosphorylation of p65 in the nucleus, which then triggers a series of physiological or pathological effects (such as the production of inflammatory cytokines, including TNF-α, IL-1β and IL-6), which eventually leads to hepatitis." (PMID 34945677, 2021). "Moreover, JGXZ treatment attenuated the inflammatory response in NAFLD model rats, manifesting as mild lobular liver inflammation and reduced expression of proinflammatory cytokines (IL-6, IL-1β, and TNF-α) in the serum and liver." (PMID 33824675, 2021). "But the IL-6 can also play an important role in the induction of hepatitis, cirrhosis, and HCC." (PMID 33435966, 2021).